PIK3CA (phosphatidylinositol-4,5-bisphosphate 3-kinase catalytic subunit alpha)
Diseases named in the same sentence as PIK3CA in open-access papers (continued):
Sharing a sentence is not in itself a finding about the gene and the disease.
breast cancer (continued). "Breast cancer patients with low COX-2 expression and PIK3CA wild type tumors had worse DFS compared to all other subgroups in celecoxib treatment, which suggest COX-2 expression and PIK3CA mutation may be good prognostic and predictive biomarkers for celecoxib therapy." (PMID 28085094, 2017). "The correlations we observed between pairs of mutated genes were often tissue specific; for example, a strong relationship between PTEN and PIK3CA was observed in breast carcinomas but not in head/neck squamous carcinomas, stomach adenocarcinomas, or ovarian cystadenocarcinomas." (PMID 29322935, 2017). "Furthermore, the oestrogen receptor‐negative breast cancer cell line BT20, which harbours an H1047R PIK3CA mutation, showed a similar effect." (PMID 27512948, 2016). "Previous studies analyzed PIK3CA mutation prognostic impact in the whole breast cancer population and not specifically in TNBC, or evaluated together exon 9 and exon 20 PIK3CA mutations, or analyzed their prognostic impact in small series (<100 patients with TNBC)." (PMID 26680641, 2015). "The results of our study suggest that the PDK-1 signaling pathway might be a promising therapeutic target for the treatment of breast cancer and that PDK1 expression should be tested in addition to PIK3CA status in patients with breast cancer prior to beginning therapy." (PMID 24739482, 2014). "In addition, in a large series of primary breast cancers analyzed with exome sequencing and reverse-phase protein arrays, PI3K pathway activation was not elevated in PIK3CA-mutated luminal A cancers." (PMID 24467828, 2014). "Moreover, when assessing breast cancer subgroups, PIK3R1 was predominantly underexpressed in HR-/ERBB2- and HR-/ERBB2+ tumors (p < 0.0000001), while PIK3CA was deregulated in only a minority of tumor samples: overexpressed in 18 (3.9%) and underexpressed in 40 (8.7%) cases." (PMID 24229379, 2013). "Conversely, the absence of PIK3CA mutation in BRCA2 associated MBCs suggests that alternate oncogenic drivers minimally contribute to tumour drive in this group, thus supporting distinct male breast cancer types." (PMID 23971979, 2013). "However, a subsequent study found that PIK3CA and PTEN mutations in breast cancer were not mutually exclusive and correlated with similar prognostic factors." (PMID 19384426, 2007). "Thus, our data of gene copy analysis indicates that gene amplification/gain of copy number of PIK3CA gene is not a frequent genetic alteration in breast cancer." (PMID 16168105, 2005). "Conversely, the effectiveness of everolimus plus exemestane on PIK3CA-mutant metastatic breast cancer (BC) after CDK4/6i failure has never been investigated in a prospective study." (PMID 41681940, 2026). "Moreover, as alpelisib—a PIK3CA inhibitor—became FDA-approved last year for PIK3CA-altered, hormone receptor–positive advanced breast cancer, this study reveals that 12% of early-onset AC cases could potentially benefit from targeting this variation and merits further study." (PMID 33295976, 2020). "Alternatively, RNMT inhibition may affect protein expression similarly in all breast cancer cell lines, regardless of PIK3CA status; cells expressing PIK3CA may have increased dependency on a subset of RNMT-dependent proteins as a mechanism of oncogene addiction." (PMID 30991934, 2019). "The aetiology of this signature is unknown, it is more dominant later in breast cancer tumourigenesis and has previously been described as arising in multiple treatment-resistant metastatic lesions in one case of TNBC resistant to both chemotherapy and a PIK3CA inhibitor." (PMID 30763338, 2019).
breast cancer (continued). "Moreover, tree shrew breast cancerous tissue has frequently been shown to have mutations in the PTEN/PIK3CA genes, with a mutation spectrum resembling a subset of human breast cancers with the PTEN/PIK3CA mutations, whereas currently no mouse breast cancer model shows this type of cancer." (PMID 28585435, 2017). "Therefore, cIAP2 may be responsible for the induction of AKT signaling in TNBCs, whereas AKT activation in luminal-type breast cancer was mainly affected by the status of PIK3CA and other factors, independent of cIAP2 expression." (PMID 29108265, 2017). "Although the intratumoral heterogeneity of the PIK3CA mutation status has not yet been investigated for ESCC, the results of our study are in line with the homogeneous distribution of the PIK3CA mutation status in the primary tumor observed in colorectal and breast cancers." (PMID 28068934, 2017). "PIK3CA mutations do not have clinical validity to predict intrinsic resistance to adjuvant tamoxifen and may therefore be unsuitable as companion diagnostic for PI3K/AKT/mTOR inhibitors in ERα- positive, postmenopausal, early breast cancer patients." (PMID 24467828, 2014). "This is not seen and may suggest alternate receptor and PIK3CA/mTOR interaction in male breast cancer or a dose-based relationship differentiated by male cancers with low estrogen at one end of the spectrum and higher levels of estrogen in females at the opposite end." (PMID 23971979, 2013). "Both were in women with breast cancer – one had a triple negative breast cancer (ER and progesterone receptor (PR) negative, HER2 negative) that was PIK3CA wild type, without PTEN loss and KRAS mutant; and the other had a ER/PR positive, HER2 negative tumor with a confirmed PIK3CA mutation (E545K)." (PMID 21317449, 2010). "The increase in expression levels of PIK3CA and IGF-R1 as well as other components of PI3K-Akt signaling pathway by FOXO3a may be sufficient for the induction Akt phosphorylation and activity if their expression levels are limiting in these breast cancer cells." (PMID 20808831, 2010). "In breast cancer alone, up to 50% of patients with Rbness in the absence of RB1 genomic alterations harbored amplifications in PIK3CA, RB (CCND1 and CCNE1), and ER signaling modules (ESR1, FOXA1, and GATA3)." (PMID 40138429, 2025). "In breast cancer cell lines, combined PIPP/PTEN knockdown increases AKT signaling and cell proliferation, independent of mutant PIK3CA, above any single PI-phosphatase knockdown." (PMID 41408399, 2025). "When used in combination with anastrozole to treat PIK3CA-mutant, ER+/HER2− breast cancer, MK-2206 was unlikely to increase the efficacy of anastrozole." (PMID 36671478, 2023). "The breast cancer biomarkers ERBB2 (HER2), ESR1(ER), PIK3CA are not significantly altered in patients with BRF2 alterations." (PMID 33176745, 2020). "Treatment with WNT5A doubled the ratio of phosphorylated to un-phosphorylated PIK3CA, showing that this non-canonical WNT pathway also operates in MCF7 breast cancer cells." (PMID 32498332, 2020). "Moreover, activating PIK3CA mutations are observed in ER negative breast cancer as well, and mTOR inhibition, combined with trastuzumab and paclitaxel, prolonged progression-free survival significantly among patients with hormone receptor negative, HER2 positive breast cancer." (PMID 28476032, 2017). "Cell lines with wildtype PIK3CA were less sensitive or lacked sensitivity to GDC-0941 completely, in agreement with studies in breast cancer, multiple myeloma, lung cancer, and endometrial cancer, where PIK3CA mutations are also frequent." (PMID 27465249, 2016). "No PIK3CA, BRCA1, or ERBB2 alterations were identified in the breast carcinoma cases." (PMID 36125633, 2023).
breast cancer (continued). "MK-2206 in this class has been recently examined in phase-II clinical trials in combination with the aromatase inhibitor, anasterozole, to treat PIK3CA-mutant ER-positive and HER2-negative breast cancer, with no apparent improvement observed with the combinational treatment." (PMID 35406424, 2022). "In addition to this, another study showed that although breast cancer cells growth is independent of PDK1, their ability for tumour initiation in vitro relies on it, regardless of their PIK3CA burden." (PMID 29064423, 2017). "Analysis of The Cancer Genome Atlas database showed that, unlike primary PIK3CA‐wild‐type and HER‐2+ breast carcinomas, PIK3CA‐mutant tumors display increased expression of AXIN2, HGF, STAT3, IGF‐1, and IGF‐2 mRNA and activation of AKT, IGF1‐MTOR, and WNT canonical signaling pathways." (PMID 28296140, 2017). "It is also noted that USP13 and PIK3CA are not amplified in breast cancer, which may interpret the tumour suppressive functions of USP13 via PTEN in breast cancer." (PMID 27892457, 2016).
colorectal cancer (415 papers, 2007 to 2026). A primary or metastatic malignant neoplasm that affects the colon or rectum. "For example, PIK3CA mutations were classified as Tier IIIA in colorectal cancer, reflecting limited evidence, but as Tier IIB in ovarian cancer, supported by early-phase trial data suggesting clinical benefit." (PMID 40973166, 2025). "While PIK3CA mutations are relatively common in breast, endometrial, and colorectal cancers, only about 3% of cases of pancreatic cancer have PIK3CA mutations." (PMID 40638603, 2025). "In colorectal cancer, the m6A modification pattern correlates with tumor mutational burden and reveals a link through which m6A, by associating with PIK3CA mutations, participates in regulating the cancer immune microenvironment and therapeutic response." (PMID 41357233, 2025). "PIK3CA mutations occur in about 15%–20% of colorectal cancer cases and are often associated with resistance to some types of chemotherapy and anti-EGFR therapy." (PMID 40083375, 2025). "For example, PTEN and PIK3CA aberrations have been detected in breast and colorectal cancers, where they are sometimes linked to therapeutic resistance or differential prognosis." (PMID 40227624, 2025). "This article provides a summary of the key detection methods for PIK3CA gene mutation, and provides an introduction to the existing colorectal cancer treatments and their practical applications in the clinic." (PMID 39555098, 2024). "Multiple PIK3CA mutations were more frequent in Black patients, including H1047L in bladder cancer, N345K in colorectal cancers, and H1047L and H1047R in ovarian cancers." (PMID 38297963, 2024). "mTOR inhibitors are mainly used in colorectal cancer patients with PIK3CA mutations, in combination with chemotherapy or other drugs, in order to improve efficacy and overcome resistance." (PMID 39555098, 2024). "The impact of PIK3CA gene mutations on the prognosis of colorectal cancer patients has been a subject of debate, with conflicting views and results." (PMID 39555098, 2024). "Another study showed that in colorectal cancer, PIK3CA gene mutations were associated with worse OS and DFS, but not with the risk of recurrence (RR) and risk of death (HR)." (PMID 39555098, 2024). "The mutation of the PIK3CA gene is closely associated with the occurrence, development, prognosis, and treatment response of colorectal cancer, making its detection clinically significant." (PMID 39555098, 2024). "Some studies have shown that PIK3CA gene mutations can increase the sensitivity of colorectal cancer to immunotherapy." (PMID 39555098, 2024). "Approximately 20% of patients living with colorectal cancer (CRC) have activating mutations in their tumors in the PIK3CA oncogene." (PMID 39401325, 2024). "PIK3CA gene mutations not only affect the pathogenesis of colorectal cancer, but also correlate with the clinical characteristics, prognosis, and treatment response of colorectal cancer." (PMID 39555098, 2024). "PIK3CA gene mutation is one of the most common mutations in colorectal cancer (CRC), affecting about 15%–20% of CRC patients." (PMID 39555098, 2024). "Some studies have shown that PIK3CA gene mutations can increase the sensitivity of colorectal cancer to mTOR inhibitors." (PMID 39555098, 2024). "Colorectal cancer with PIK3CA mutations often accompanies mutations in genes such as KRAS, BRAF, PTEN, AKT1, all of which are components of the PI3K signaling pathway or MAPK signaling pathway." (PMID 39555098, 2024). "The impact of PIK3CA gene mutations on the clinical characteristics and prognosis of colorectal cancer is not fully understood, and there are certain differences and contradictions in the results of different studies." (PMID 39555098, 2024).
colorectal cancer (continued). "This section will review the relevance of PIK3CA gene mutations to the clinical and pathological characteristics of colorectal cancer, as well as the impact of PIK3CA gene mutations on the prognosis of colorectal cancer patients and possible mechanisms." (PMID 39555098, 2024). "Our manuscript represents the largest data regarding PIK3CA mutation prevalence in advanced colorectal cancer, demonstrating that PIK3CA multi-hit mutations are present in 1.7% of advanced CRC." (PMID 39401325, 2024). "Recent studies have shown that PIK3CA mutations in colorectal cancer led to significant metabolic reprogramming." (PMID 39555098, 2024). "Some studies have found that colorectal cancer patients with PIK3CA gene mutations have poor efficacy when using anti-EGFR monoclonal antibodies, with significantly shortened progression-free survival and overall survival." (PMID 39555098, 2024). "In colorectal cancer, the most commonly found alterations of this pathway include PIK3CA mutations and loss of PTEN activity." (PMID 38672636, 2024). "The impact and mechanism of PIK3CA gene mutation on tumor-associated antigen vaccines or cell therapy in colorectal cancer mainly involve several aspects." (PMID 39555098, 2024). "A meta-analysis focused on the prognostic role of PIK3CA mutation in colorectal cancer showed that PIK3CA mutation has neutral prognostic effects on overall and progression-free survival." (PMID 39768623, 2024). "In patients with colorectal cancer, mutated-PIK3CA was associated with prolonged survival when aspirin was regularly taken." (PMID 39768623, 2024). "In colorectal cancer, the alpha catalytic sub-unit of the PI3K kinase gene is frequently mutated, and PIK3CA was mutated in 30.8% of CDX2-suppressed colorectal cancers compared to 23.3% of non-CDX2-suppressed colorectal cancers (Fisher’s exact test p = 0.25)." (PMID 39452477, 2024). "In colorectal cancer, mutations in PIK3CA are associated with resistance to therapy by anti-EGFR monoclonal antibodies." (PMID 39768623, 2024). "Some studies have shown that the TMB of colorectal cancer patients with PIK3CA gene mutations is significantly higher than that of patients with wild-type PIK3CA." (PMID 39555098, 2024). "PIK3ACA mutations are associated with a worse response to first-line chemotherapy and a phase I clinical trial has shown evidence for the sensitivity of PIK3CA mutated colorectal cancer to the PIK3a-selective inhibitor." (PMID 37483495, 2023). "With the development of sequencing technology, tumor-related genes are being increasingly identified, and RAS, BRAF, and PIK3CA mutations are being detected in colorectal cancer." (PMID 38201315, 2023). "PIK3CA/p110α is one of the most frequently mutated oncogenes and a key therapeutic target in colorectal cancer." (PMID 37689735, 2023). "Previous studies have shown that When PIK3CA mutates, the glutamate pyruvate transaminase 2 in colorectal cancer (CRC) cells is significantly upregulated, thereby affecting the reprogramming of glutamine metabolism." (PMID 37719859, 2023). "Mutations that constitutively activate RAS, BRAF, or PIK3CA are most common among colorectal cancers with frequencies of 30–50%, 10–15%, and 10–20%, respectively." (PMID 37791907, 2023). "Nusrat and other researchers recently reported that microsatellite stable colorectal cancer patients with PIK3CA mutations benefited from immunotherapy." (PMID 36333792, 2022). "Epidemiological studies have found that low‐dose aspirin reduces the risk of colorectal cancer recurrence in patients treated for PIK3CA‐mutant cancers." (PMID 34245130, 2022).